ISG15 (ISG15 ubiquitin like modifier)
Diseases named in the same sentence as ISG15 in open-access papers (continued):
Sharing a sentence is not in itself a finding about the gene and the disease.
viral infection (continued). "The ISG15 protein experiences significant upregulation in response to robust stimulation from viral infections within the body." (PMID 38791729, 2024). "In the beginning of the innate response to viral infection, ISG15 has been shown to be substantially increased as an effector and signaling molecule." (PMID 37007947, 2023). "The interferon-stimulated gene 15 (ISG15) plays a critical role in the innate immune response against microbial and viral infections through regulating cytokine release and suppressing IFN signaling." (PMID 37628641, 2023). "Deleting interferon-γ stimulated gene 15 (ISG15) in human cells results in hyperactive interferon signaling, mimicking a viral infection." (PMID 37919735, 2023). "Our study has established that in the white matter of untreated HAND subjects, the expression of STAT1, IFIT3, and ISG15 was upregulated as expected due to viral infection." (PMID 36841839, 2023). "ISG15 can also play an antiviral role in immunomodulatory, regulating the host's damage and repairing responses during viral infection." (PMID 36774376, 2023). "As an interferon-induced protein, either by directly interacting with viral proteins or regulating the host cells’ pathway, ISG15 often plays an antiviral role in the process of virus infection." (PMID 37637123, 2023). "As expected, some of the interferon-stimulated genes (e.g., ISG15) provided much more discriminating power for patients with a viral infection as compared with those with a purely bacterial infection." (PMID 37009900, 2023). "The mRNA expression levels of IL-6, IL-18, IFN-α, IFN-β, and ISG-15 in the peripheral blood mononuclear cells (PBMCs) were significantly up-regulated during viral infection." (PMID 37632087, 2023). "As one of the most highly upregulated genes during viral infections, ISG15 acts as both an effector and a signaling molecule in various phases of the innate immune response." (PMID 37017816, 2023). "Increased expression of IFN-stimulated gene 15 (ISG15) and subsequently increased ISGylation are key factors in the host response to viral infection." (PMID 36439639, 2022). "While cells mount an ISG15-dependent response to trigger defences against viral infection, many viruses have in turn co-evolved strategies to counter them." (PMID 36416643, 2022). "Interferon stimulated gene 15 (ISG15), an ubiquitin-like protein that plays a multifaceted role in viral infections and viral induced inflammation, was among the most strongly upregulated in all four tested conditions." (PMID 35962146, 2022). "During viral infection, interferon and ISGs expression levels only modestly changed, however KD/KO cells generally exhibited decreased magnitudes of expression of ISG15, IFNλ1, and ISG56 compared to WT cells." (PMID 35085371, 2022). "Most of the information on ISG15 has come from studying viral infection, where ISGylation of viral and host proteins limits viral replication." (PMID 36216822, 2022). "Humans that lack ISG15 have chronic, low levels of antiviral ISGs, and ensuing broad-spectrum resistance to viral infection." (PMID 35333911, 2022). "Gene module 3 comprised type I interferon–responsive genes characteristic of stimulated macrophages/monocytes reacting to an active viral infection, such as ISG15, IFIT2, and IRF7." (PMID 35039442, 2022). "These ISRE elements along with transcription factors in IFN signalling like IRF3, regulate ISG15 expression in response to IFN or viral infection." (PMID 36419602, 2022). "Further validation was performed using Nbs1f/f cell lines in which the de-ISGylase, Usp18, was disrupted via CRISPR-Cas9 editing and an exogenous doxycycline inducible 6HIS-ISG15 integrated via lenti-viral infection (Usp18−/−+6his-ISG15)." (PMID 36216822, 2022). "Meanwhile, other research have indicated that ISG15 plays a key role in mediating and regulating host response to viral infection." (PMID 36094909, 2022).
viral infection (continued). "ISG15 also called Ubiquitin-like protein ISG15 is an early mediator of signaling induced by Type I IFNs and elicits innate immune response to viral infections by conjugation/ISGylation of its targets like MX and IFIT48–51." (PMID 35115549, 2022). "In summary, our results highlight that ISG15 controls BMDM lipid metabolism during viral infections, suggesting that ISG15 is an important host factor to restrain VACV impact on cell metabolism." (PMID 36453897, 2022). "UBE2L6, the ISG15 E2 transferring enzyme, was detected to be fivefold more abundant after viral infection." (PMID 35281454, 2022). "These genes were involved in IFN-induced antiviral mechanisms such as OAS and ISG15-signaling, which are induced rapidly upon viral infection." (PMID 35618845, 2022). "HERC6, IFI6, ISG15, and MX1 encode for proteins induced by type I interferons, such as IFN-α, IFN-β, IFN-ω, and are typically produced by host cells in response to viral infection." (PMID 35197051, 2022). "Five hub genes shared by RA, COVID-19, and SAB were IFI44, OAS1, IFI44L, ISG15, and HERC5, and they were found to be closely associated with the immune system response to viral infection and bacterial infection using Metascape analysis." (PMID 36189314, 2022). "The second peak is IFN dependent in which ISG15 is produced as an inducible product of type I IFN signalling cascade upon viral infection." (PMID 36419602, 2022). "It has been reported that ISG15 can inhibit different stages of viral infection, for example, entry, latency, replication, posttranslational modification and processing, egress and trafficking, assembly and budding, and release." (PMID 36036587, 2022). "Interferon-stimulated gene 15 (ISG15) is strongly upregulated during viral infections and exerts pro-viral or antiviral actions." (PMID 36315588, 2022). "In our study of 16HBE cells infected with SARS-CoV-2, we found that the level of CXCL10 transcription increased gradually with virus infection progression but that relative expression of ISG15, NF-κB, IFN-α and IFN-β increased within 6 h and then decreased." (PMID 36560452, 2022). "Our studies establish the importance of free ISG15 in IFNα-induced antiviral immunity and in the control of viral infections." (PMID 36315588, 2022). "As shown in previous study, ISG15 plays a key role in mediating and regulating host response to viral infection." (PMID 36094909, 2022). "In vitro studies in mouse cells have demonstrated an antiviral role for ISG15 during several viral infection, although there are some reports of viruses displaying no enhanced replication when ISG15 is deficient." (PMID 36315588, 2022). "Recent investigations demonstrated that ISG15 acted as a negative regulator of type I IFN signaling exerted antiviral response during viral infection." (PMID 36315588, 2022). "ISG15 is one of dozens of ISGs that are induced during the response of cells to virus infection and innate anti-viral immune responses likely trigger ALS." (PMID 35280283, 2022). "The interferon-stimulated gene 15 (ISG15) is one among the early and highly expressed ISGs upon viral infection." (PMID 36419602, 2022). "Identifying species-specific immune genes such as ISG15 in seabass can shed light on the host-viral protein interactions during viral infection and help develop better antiviral strategies." (PMID 36419602, 2022). "The ISG15 gene is strongly induced and the protein is rapidly produced in response to viral infections and it has been shown to interfere with replication of several viruses, including Influenzas A and B, and to modulate host immunity." (PMID 33931718, 2021). "The conjugation of ISG15 to MDA5 upon virus infection serves as a trigger to promote MDA5 oligomerization and antiviral immunity, suggesting that MDA5 ISGylation serves an analogous role to the K63-linked ubiquitination of RIG-I." (PMID 33530371, 2021).
viral infection (continued). "Herc5, induced by the type I IFNs or viruses, functions as an ISG15 E3 ligase to promote overall ISGylation in response to viral infection and plays a role in host antiviral response." (PMID 34680952, 2021). "The rapid induction of ISG15 in response to viral infection has significant impacts on the cellular environment." (PMID 34207696, 2021). "The expression of ISG15 increases in response to many viral infections, including influenza A, Ebola, hepatitis B and C, human immunodeficiency virus 1, human papillomavirus, West Nile, and Zika." (PMID 34372519, 2021). "OASL and SAMD9L have been shown to be important in viral infection and innate immunity, but the mechanism of their action is different from that of ISG15." (PMID 34920753, 2021). "ISG15 and ISGylation are both strongly upregulated by type I interferons and play putative key roles in host innate immunity against viral infection." (PMID 33671165, 2021). "Interferon-stimulated gene 15 (ISG15), one of the most strongly induced ISGs during viral infection, was found in our previous study to play an antiviral role in PRV replication." (PMID 34680952, 2021). "ISG15 is one of the most highly induced ISGs in viral infections, and it has also been found to be directly induced by IRF3/IRF7, independent of IFNs (46, –, 48)." (PMID 33785572, 2021). "Perng and Lenschow discussed the role of ISG15 in regulating host damage and repair responses and immune responses and provided new insights for ISG15 in shaping the host's response to viral infections." (PMID 35002537, 2021). "The expression of ISG15 can be promoted by external stimuli, such as bacterial and viral infection and tumorigenesis." (PMID 34659576, 2021). "ISG15 is a ubiquitin-like protein which is induced by viral infection, and IFN-α and -β, and can conjugate to target proteins such as IRF3." (PMID 34064193, 2021). "The top genes in the individual LIMMA analyses that were differentially expressed in peripheral blood samples of patients hospitalized with viral infection vs. bacterial (baseline in the model) infection were ISG15, TIMM10, IFI27, IFI44L and OAS2." (PMID 34593881, 2021). "In recent years, many studies have explored the role of ISG15 in antiviral innate immunity, especially in the process of viral infection, and the role of ISGylation of host and viral target proteins in immune defense." (PMID 34901029, 2021). "It is known that either ubiquitin or ISG15 are covalently bonded to target proteins during the cellular response to viral infection." (PMID 34198325, 2021). "Interferon-stimulated gene product 15 (ISG15) is a ubiquitin-like protein, which is critical for controlling microbial infections, especially viral infection." (PMID 34277631, 2021). "Third, viral infections activate a host innate immunity mechanism, through interferon-stimulated gene 15 (ISG15), that specifically disrupts virus budding complexes." (PMID 33731460, 2021). "Although IFN-γ is critical for activating both innate and adaptive immune responses to virus infection in vivo, little is known regarding the true function of extracellular ISG15 or how it participates in activation of intracellular signaling mechanisms." (PMID 32927637, 2020). "ISG15 also plays a role in damage repair after clearing viral infection and can regulate cellular processes such as autophagy and metabolism." (PMID 32667958, 2020). "During viral infections, ISGylation seems to target a high number of proteins at the translational level, either as an activating or inhibitory signal, while free ISG15 can also act as a cytokine." (PMID 32429099, 2020). "The results demonstrated that carvedilol promoted the production of Ifnb, Isg15, and Ccl5 and reduced the virus titers in the spleens, livers, and lungs of WT mice after virus infection." (PMID 33243993, 2020).
viral infection (continued). "Although other Lpro residues mediating its interaction with ISG15 have been recently identified, we propose that LproW105 is important for modulating viral infection kinetics." (PMID 32295921, 2020). "Among the ubiquitin-like protein modification, the role is well-known in ubiquitin, SUMO, NEDD8, and ISG15 during the viral infection, while for others such as, FAT10, URM1, UFM1, and ATG, very few reports are available." (PMID 33396899, 2020). "Mice infected with the mutated PLP virus showed a 76% survival, attributable to ISG15 restoration, while the wild type PLP virus infection resulted in more than 80% mortality." (PMID 32429099, 2020). "ISG15 expression is normally induced in host cells by a variety of factors, including viral infection, TLR ligands such as lipopolysaccharide and poly IC, tumor necrosis factor-α, or type I, II, and III IFNs." (PMID 33024031, 2020). "ISG15 conjugation plays an anti-viral role during viral infection by conjugation to viral proteins or hosts cellular proteins, leading to inhibition of enzymatic activity, viral replication inhibition, translational shutoff, and metabolic reprogramming." (PMID 33396899, 2020). "Early work on ISG15 depended on mouse models and showed that expression of ISG15 protected mice from viral infection." (PMID 32667958, 2020). "ISG15 is best known for its role in viral infection, and in contrast, there are only a few studies describing its role in bacterial and fungal infections (54, –, 58)." (PMID 33024031, 2020). "ISG15 has been proposed as an efficient host effector that defends against viral infections including that of human cytomegalovirus, human immune deficiency virus (HIV), West Nile virus, and porcine reproductive and respiratory syncytial virus." (PMID 32093773, 2020). "The increase in the expression of ISG15 is found after type I interferon stimulation and viral infection." (PMID 31665046, 2019). "Other genes that are well-known to be upregulated with early viral infection such as ISG15 and interleukin (IL)-1β were also commonly upregulated on day 1 p.i. along with NADPH oxidase 1 (NOX1)." (PMID 31635289, 2019). "One proposed mode of action of ISG15 is cotranslational modification of nascent polypeptides following viral infection as mediated by the IFN-induced E3 HERC529." (PMID 31772204, 2019). "Canonical induction of ISG15 occurs following Type I interferon activation or viral infection; however, ISG15 can also be induced by a variety of other stimuli, such as retinoic acid, LPS, and genotoxic stress." (PMID 31772204, 2019). "Whereas, in contrast to RV, IAV reduces the pluripotency of iPSCs, both virus infections induce ISG15 and IFN λ1, highlighting this observation as an innate immune mechanism that is already developed in iPSCs." (PMID 31405163, 2019). "In other contexts, such as upon viral infection or oxidative stress, ISG15 and USP18 can reach high levels." (PMID 30858391, 2019). "ISG15 is an innate immune and interferon-induced protein that plays a central role in response to viral infection." (PMID 30641486, 2019). "ISG20 and ISG15 possess direct antiviral activity, and have been shown to mediate protection in several different viral infection models." (PMID 30158514, 2018). "Recently identified as an HCMV-encoded regulator of ISG15 and ISGylation, IE1 (IE72, pUL123) was observed to strongly inhibit ISG15 transcription levels during viral infection and enable viral evasion of the ISGylation response." (PMID 30134546, 2018). "ISG15 plays a key role in the innate immune response to viral infection either via its conjugation to a target protein (ISGylation) or via its action as a free or unconjugated protein." (PMID 30374051, 2018). "ISG15, a well-studied component of the type 1 interferon-mediated response to viral infection, is a mediator of ISGylation, a protein modification similar to ubiquination." (PMID 28588308, 2017).
viral infection (continued). "IFIT1, as well as ISG15, are interferon-induced genes reported to be activated immediately and robustly upon viral infection." (PMID 28869524, 2017). "This is in agreement with the fact that the major host response to viral infection is the production of IFNs, which in turn stimulate ISG15 expression." (PMID 27626177, 2016). "More interestingly, the function of ISG15 (and ISGylation) during viral infection seems to be restricted to specific hosts." (PMID 27867263, 2016). "We suggest that one of the roles of ISGylation at early stages of viral infection in humans is to sequester free ISG15, thereby allowing IFN signalling to occur." (PMID 27193971, 2016). "Our results indicate that HCMV has evolved countermeasures to suppress ISG15 transcription and protein ISGylation, highlighting the important of the interplay between virus and ISG15 signaling during virus infection." (PMID 27564865, 2016). "The Mx1, Isg15, and Ddx58 mRNA expressions levels were significantly increased after virus infection." (PMID 27826541, 2016). "This study highlights that ISGylation is a critical innate immune response against HCMV infection and interfering with ISG15-mediated anti-viral immunity is critical for productive viral infection." (PMID 27564865, 2016). "Given that ISG15 and the enzymes involved in ISGylation are strongly induced upon virus infection, understanding the interplay between virus and ISGylation is an important issue in virus-host interaction." (PMID 27564865, 2016). "The RIG-I-MAVS pathway, through the production of type I IFN and subsequent production of ISGs such as Mx1, PKR, ISG15, RNase L, etc., restricts viral infection in various cellular compartments of the lungs." (PMID 27438481, 2016). "ISG15 inhibits the replication of influenza A virus and the Japanese encephalitis virus and controls the proinflammatory response against viral infection." (PMID 27344170, 2016). "In light of these findings, further studies are needed to determine the precise mechanism of action of unconjugated ISG15 in virus infection." (PMID 26361997, 2015). "Component enzymes of the ISG15 cascade are transcriptionally upregulated by multiple pathways involved in sensing immune-related stress, such as virus infection." (PMID 26361997, 2015). "On the other hand, neuron- and skeletal muscle-specific NEDD4 KO mice are viable, and NEDD4 is naturally inhibited by ISG15 during virus infections, perhaps suggesting that short-term inhibition of NEDD4 can occur without adverse effects." (PMID 26263374, 2015). "Associated with transcriptionally regulatory network, ISG15 expression which was targeted by STAT5B and GATA2 factors was induced by virus infection." (PMID 25907774, 2015). "ISG15 expression is induced in many cell types by IFNs, viral infection, bacterial endotoxins, and genotoxic stress." (PMID 24489947, 2014). "ISG15 is a type I interferon regulated gene that is induced by viral infection through the JAK/STAT signaling pathway." (PMID 25238261, 2014). "Conjugation of ISG15 to target proteins (ISGylation) is dramatically up-regulated following cellular stimulation by interferons or viral infection." (PMID 24854014, 2014). "Here, we describe a novel function of ISG15 in the control of macrophages activation, phagocytosis and apoptosis in response to viral infection." (PMID 24137104, 2013). "During viral infection in mice, ISG15 exists in three different forms: unconjugated within the cell, conjugated to target proteins and released into the serum." (PMID 24137104, 2013). "The ubiquitin-like protein (UBL) ISG15 is a critical IFN-induced antiviral molecule that protects against several viral infections, but the mechanism by which ISG15 exerts its antiviral function is not completely understood." (PMID 24137104, 2013).